CCNB1 (cyclin B1)
Diseases named in the same sentence as CCNB1 in open-access papers (continued):
Sharing a sentence is not in itself a finding about the gene and the disease.
cancer (continued). "CCNB1 is a cycle-like protein that regulates cell cycle G2/M, and its expression imbalance is one of the causes of malignant tumor proliferation, including HCC." (PMID 32789471, 2020). "Cyclin B1 and Cyclin D1 control mitosis, cell adhesion, and migration within the cell cycle; hence, they are associated with cancer cell development and metastasis." (PMID 32872198, 2020). "Combining the scores of cytoplasmic BUB3 and CCNB1 improved risk stratification when integrated with the Cancer of the Prostate Risk Assessment post-Surgical (CAPRA-S) score (difference in concordance index = 0.024, 95% CI 0.001–0.05)." (PMID 31801961, 2020). "We found that proteasome inhibition in SMARCB1-deficient cancer cell lines results in G2/M arrest due to inappropriate degradation of cyclin B1." (PMID 30860482, 2019). "Our finding indicated that CuE in the explored cancer cells led to down‐regulation of the association of the cyclin B1/CDC2 complex and the up‐regulation of GADD45β." (PMID 30912292, 2019). "The silencing of the cyclin-B1 gene caused induction of growth arrest at G2 phase and stopped cancer cell division." (PMID 29861465, 2018). "A plenty of studies revealed that cyclin B1 is implicated in the differentiation, growth, apoptosis, metastasis and chemoresistance of cancer cell." (PMID 27903976, 2017). "This loss of cyclin B1 and stimulation of apoptosis by CFMs in RCC cells would be consistent with our prior findings demonstrating promotion of G2M cell cycle arrest, loss of mitotic cyclin B1, and apoptosis stimulation by CFMs in other cancer cell models." (PMID 29285223, 2017). "In contrast, the genes encoding cyclin-A1, -B1, -E1 and -E2, i.e. Ccna1, Ccnb1, Ccne1 and Ccne2, were up-regulated in malignant tumors." (PMID 25900242, 2015). "Over-expression of Cyclin B1 is associated with a number of different cancers including breast, oesophageal squamous cell, non-small cell lung and renal cancer." (PMID 23874748, 2013). "The increased proliferation seen in PAH-PASMC is associated with a KLF-5-dependent up-regulation of cyclin B1, confirming previous findings in systemic vessels and cancer." (PMID 21951574, 2011). "Notably, CCNB1 is frequently observed to be overexpressed or amplified in various types of cancer, and this aberrant expression is often associated with unfavorable prognoses and resistance to chemotherapy." (PMID 41439111, 2025). "The dysregulation of cyclin B1 is linked to the progression of various cancers." (PMID 39062041, 2024). "Furthermore, elevated CCNB1 expression levels were significantly linked to the progression of TNM stages in several cancer types." (PMID 38581717, 2024). "Our data exhibited that CCNB1 has a mutation rate of 1.3% in pan-cancer." (PMID 38581717, 2024). "In addition, genes that promote cell cycle progression such as CCNE1 and CCNB1, which encode cyclin E1 and cyclin B1, respectively, are also crucial players in cancer cell proliferation." (PMID 38538106, 2024). "As an epigenetic change, DNA methylation shows that CCNB1 is a more suitable cancer risk biomarker." (PMID 36040381, 2022). "On the other hand, cyclin B1 is important in regulating the G2-to-M phase transition, which is essential for cellular mitosis, and altered expression of cyclin B1 is implicated in the aggressive proliferation of cancer cells." (PMID 35334562, 2022). "CCNB1 is linked to invasion, metastasis, and poor prognosis of several cancers." (PMID 33190424, 2021). "Furthermore, abnormal CCNB1 expression is often associated with a variety of cancers, and CCNB1 can be used as a biomarker to predict cancer." (PMID 33632229, 2021). "Moreover, FOXM1 binds to known FOXM1 targets in cancer cells: the CCNB1 and PLK1 gene promoters (CCNB1 encodes CYCLINB1 and PLK1 encodes Polo kinase 1, respectively) in WG4 cells as demonstrated by ChIP-qPCR." (PMID 34131149, 2021).
cancer (continued). "Retinoblastoma gene in cancer, another pathway associated with “Evasion of growth suppressors”, was also upregulated, with strong overexpression of pathways members leading to G1/S transition (CCNB1, CDK1) and mitotic spindle association (TTK)." (PMID 33917186, 2021). "Similarly, overexpression of PER1downregulated the levels of Wee1, CcnB1 (encodes cyclin B1), and Cdk1 (encodes Cdc2) mRNA and suppressed growth in cultured cancer cells." (PMID 32372973, 2020). "Recently, several studies have reported that the expression of cyclin B1 may be associated with the prognosis of cancer." (PMID 29221213, 2017). "We have found that CFMs attenuate cyclin B1 levels and promote G2M arrest in a variety of cancer cell types, and the fact that SFN caused G2M arrest in part by targeting Cyclin B1 it is likely that, similar to SFN, CFMs also stimulate G2M arrest in our parental and Everolimus-resistant RCC cells." (PMID 29285223, 2017). "High expression of Cyclin B1 is associated with high breast tumor grade, larger tumor size and higher metastasis probability, and therefore, can be used as a tool to determine the prognosis of cancer patients." (PMID 27462423, 2015). "Additionally, CCNB1 has been implicated in the pathogenesis of various cancers." (PMID 38581717, 2024). "Previous and recent data suggested that both USP22 and CCNB1 are members of these signature gene families, the upregulation of which is associated with the development, progression and metastasis as well as chemotherapeutic resistance of several types of human cancers." (PMID 27030811, 2015). "The results indicated that compound 150441 effectively inhibited the expression of Aurora A and cyclin B1 and the activation of PLK1, CDK1, and CDC25C, causing cancer cell arrest in the G2 phase." (PMID 40126184, 2025). "Decreased expression of CDC25C, CDK1, and CCNB1 inhibited the transfer of cell cycle from G2 phase to M phase, resulting in the inhibition of cancer cell proliferation." (PMID 40313621, 2025). "The observed effects align with earlier work demonstrating the efficacy of MBZ in arresting cancer cells at the G2/M phase and markedly lowering the expression level of Cyclin B1 at 48 h of MBZ treatment in TNBC." (PMID 39851541, 2025). "This compound is known to induce cell apoptosis through an intrinsic pathway involving Bax, Bcl-2 and caspase-3 proteins, and it promotes cell cycle arrest by regulating mediators such as cyclin A, cyclin B1 and cyclin D1 in various cancer cells." (PMID 40005281, 2025). "Our results further demonstrated the ability of CCNB1IP1 to ubiquitinate cyclin B1, thus targeting the E3 ubiquitin ligase involved in cell cycle regulation is expected to provide new therapeutic strategies for cancer therapy." (PMID 39849382, 2025). "Previous studies have reported elevated CCNB1 expression across multiple cancers, a finding that is in line with our observations in CRC." (PMID 41614789, 2025).
cancer (continued). "This suggests that CREPT regulates Cyclin B1 at the transcriptional level, delays the transition to G2/M, and ultimately hinders cell growth in cancer cells." (PMID 40723282, 2025). "ATG10 promotes cancer growth and metastasis by modulating epithelial-mesenchymal transition and cell cycle regulators such as cyclin B1, CDK1 and CDK2." (PMID 40313244, 2025). "These molecular alterations suggest that EVO-induced arrest results from inactivation of the cyclin B1-cdc2 complex and enhancement of p21-dependent checkpoint control—key pathways that suppress cell cycle progression in rapidly dividing cancer cells." (PMID 41209568, 2025). "Previous studies have investigated the relationships between the CCNB1 expression and prognosis in various cancers." (PMID 41614789, 2025). "Specifically, STOX1‐A overexpression increased both the mRNA expression and promoter luciferase activity of CCNB1 (cyclin B1), indicating its function as a transcriptional activator in this cancer type." (PMID 40567110, 2025). "Further, we examined the mRNA levels of CCNB1 across 33 cancer types compared to their matched normal tissues using the GEPIA database." (PMID 38581717, 2024). "By integrating microarray and RNA sequencing datasets, we found that CDK1, CCNA2, and CCNB1 were significantly upregulated in OS samples than non-cancer samples." (PMID 38164289, 2024). "In this study, our findings revealed that a combination treatment of cisplatin and KK4-PSE promoted cancer cell growth inhibition through up-regulating p21 and cyclin B1." (PMID 39123546, 2024). "The results from both Sangerbox and the GEPIA database exhibited consistent trends in CCNB1 expression profiles across various cancer types." (PMID 38581717, 2024). "Analysis from the HPA database indicated that CCNB1 protein expression was elevated in 12 cancers, consistent with the mRNA expression profiles in these cancer types." (PMID 38581717, 2024). "Our findings demonstrated CCNB1 hypomethylation in specific cancers, suggesting a potential involvement in tumorigenesis by promoting cellular transformation." (PMID 38581717, 2024). "Within the GEPIA database, CCNB1 mRNA levels were significantly higher in 22 types of cancer, while the Sangerbox database showed significant upregulation in 32 cancer types." (PMID 38581717, 2024). "A biomarker study involving 165 BC patient samples analyzed the expression levels of four genes (CCNB1, KIF4A, TPX2, and TRIP13) and their association with clinical characteristics, revealing a correlation between elevated CCNB1 expression and cancer stage." (PMID 39795587, 2024). "Subsequently, we examined the association between CCNB1 expression and MSI across various cancers, uncovering positive correlations in STAD, MESO, UCEC, ACC, SARC, KIRC, LIHC, and COAD." (PMID 38581717, 2024). "Our findings suggest that CCNB1 has the potential to serve as an independent prognostic biomarker for numerous cancers, with its expression level varying across different cancer types." (PMID 38581717, 2024). "In this study, we conducted a pan-cancer analysis of CCNB1 to investigate its prognostic significance and immunological aspects." (PMID 38581717, 2024). "The expression of CCNB1 is regulated by a variety of molecular mechanisms that differ across cancer types." (PMID 38581717, 2024). "For example, CCNB1 has been identified as one of the top genes strongly correlated with glycolysis in various cancers." (PMID 38794139, 2024). "We conducted a comprehensive pan-cancer analysis to investigate the previously unexplored, crucial role of CCNB1." (PMID 38581717, 2024). "The Cox regression analysis revealed that high CCNB1 expression significantly correlated with shorter DFS in four cancer types, namely, LIHC, KIRP, SARC, and MESO, out of the 28 cancer types evaluated." (PMID 38581717, 2024). "Analysis of CCNB1 genetic alterations was conducted using the cBioPortal database (TCGA, Pan-cancer Atlas)." (PMID 38581717, 2024).
cancer (continued). "In summary, our research revealed widespread overexpression of CCNB1 across various cancer types and demonstrated its correlation with clinical prognosis." (PMID 38581717, 2024). "To investigate the mRNA expression landscape of CCNB1 across various cancers, we comprehensively analyzed its mRNA levels using interactive body maps from the GEPIA database." (PMID 38581717, 2024). "Although this result is surprising, such differences in cyclin B1 phosphorylation depending on the type of cancer cells have also been documented by other authors." (PMID 38675591, 2024). "This study represents the first comprehensive pan-cancer investigation of CCNB1 expression, comparing it to corresponding normal tissues." (PMID 38581717, 2024). "CCNB1 gene expression was found to be significantly increased in the high-stage cancer patient group." (PMID 39795587, 2024). "In the present study, we found that CCNB1 was upregulated in 321 OS samples than 66 non-cancer samples; the larger sample size that we used in our analysis gives our study stronger statistical power compared to the small sample sizes in prior studies." (PMID 38164289, 2024). "Elevated CCNB1 expression correlated with decreased overall survival (OS) in 11 cancer types and disease-free survival (DFS) in 12 cancer types." (PMID 38581717, 2024). "Molecular docking predictively simulated the interactions between these compounds and CDK2 and CCNB1 proteins involved in cancer pathways and progression." (PMID 37887429, 2023). "High expression of CCNB1 results in the continuous cell cycle and division of cancer cells, promoting their migration and metastasis to distant sites." (PMID 36418517, 2023). "CDK-2 and CCNB1 are two key molecules involved in cell cycle regulation, and they have been explored as potential anti-cancer targets due to their critical roles in controlling cell division." (PMID 37887429, 2023). "This study provides a comprehensive analysis of the expression and methylation status of CCNB1 across several forms of cancer and provides further insight into the mechanistic pathways regulating Cyclin B1 in the tumorigenesis process." (PMID 37758792, 2023). "Next, we performed RT-PCR in 37 WT cancer tissues and paired adjacent normal kidney tissues to verify the expression of CCNB1." (PMID 37592341, 2023). "Despite reports of the deleterious effects of increasing cyclin B1 levels in cancer cells, in our work, we have shown that cell cycle arrest is accompanied by an increase in cyclin B levels." (PMID 37759511, 2023). "We comprehensively evaluated the expression and promoter methylation of CCNB1 across 38 cancers based on RNA sequencing data obtained from the Cancer Genome Atlas (TCGA)." (PMID 37758792, 2023). "In breast cancers, MYBL2 can transactivate the MYC and CCNB1 genes by binding their promoters and expediting the cell cycle of cancer cells." (PMID 36814821, 2023). "Cyclin B1 and D1 regulate cell mitosis, adhesion, and cell cycle migration, thereby participating in cancer progression and metastasis." (PMID 36830941, 2023). "WDR4 plays an oncogenic role in HCC by positively regulating the expression of CCNB1 to induce the G2/M cell cycle transition and inhibit apoptosis, which promotes the proliferation ability of cancer cells." (PMID 37283791, 2023). "To corroborate this result, we also evaluated the expression of CDC25A, CDK1 and CCNB1, the most important cell cycle regulatory proteins involved in cancer progression." (PMID 37504902, 2023). "Cancer cells can exit mitotic arrest via a process known as mitotic slippage to avoid cell death, for instance by degrading cyclin B1, with the consequential increase in chromosomal instability and aneuploidy." (PMID 37468549, 2023). "Through this work, we performed a pancancer analysis of the levels of CCNB1 and dissected aspects of regulation and how this correlates with cancer prognosis." (PMID 37758792, 2023).
cancer (continued). "Induction of G2/M arrest represented by a reduction of cyclin B1 level in SKOV-3 cancer cells was subsequently seen to be an effect of RES treatment." (PMID 37242538, 2023). "Only a small subset of these genes was differentially expressed in multiple carcinomas, including genes involved in cell cycle progression such as CCNB1, CCNE1, CCNE2, and FOXM1." (PMID 37345032, 2023). "The overexpression of cyclin B1 is negatively correlated with a poor prognosis in different types of cancer and is involved in tumorigenesis." (PMID 36431014, 2022). "Taken together, the results indicate that AE and QR are the pivotal active compounds of THCQF, and CCNB1 is the main molecular target through which THCQF exerts its anticolon cancer effects." (PMID 35479514, 2022). "The transcriptome data of 33 types of cancer and normal tissues in the TCGA database was used to extract CCNB1 expression." (PMID 36040381, 2022). "The entry of cancer cells into mitosis is regulated by activation of Cyclin B1-Cdc2 at the G2/M transition." (PMID 36561342, 2022). "CyclinB1 (CCNB1) is a highly conserved family of cyclins that is detected in nearly all human tissues and many of cancer types." (PMID 36040381, 2022). "In cancer cells, expression of cyclin B1 was lower, but cyclin D1 was higher than in HUMEC, indicating disturbances in G2-M and G1-S transition in MCF-7 cells." (PMID 36619302, 2022). "Expression levels of cell-cycle markers such as CDK4 and cyclin B1 were also found to be reduced in both the cancer cell lines as a result of treatment with KRAS G12C inhibitors or their combinations with selinexor." (PMID 35573474, 2022). "Evidently, it is likely that the combinations of selinexor and KRAS G12C inhibitors induce cell-cycle arrest in KRAS G12C–mutant cancer cells by downregulating cyclin B1 and CDK4 expression and upregulating the accumulation of TSP Rb in the nucleus." (PMID 35573474, 2022). "CCNB1 has been discovered to be strongly expressed in 19 cancer types, including BC, while low expressed in normal tissues." (PMID 36040381, 2022). "After mid mitosis, cell cycle proteins are separated from CDK, and in the presence of APC, M phase cyclin A and cyclin B are degraded by the proteasome through ubiquitination-dependent pathway, and CCNB1 is also known to promote cancer development." (PMID 36479313, 2022). "6-O-angeloylplenolin, coronopilin, pulchelloid A, and hymenoratin, 5/7-bicyclic pseudoguaianolide SLs also induce high p-Cdk1 and/or Cdk1 and cyclin B1 expression in certain cancer cell types." (PMID 35651747, 2022). "In parallel, cyclin B1 (CycB1), which is often upregulated in cancer and leads to the transition of the cells from G2 into M phase, was markedly decreased." (PMID 35884996, 2022). "Following that, the expression level of hub genes (CCNB1) was investigated using Q-PCR.The results revealed that the CCNB1 was highly expressed in the carcinoma tissues, consistent with our results." (PMID 36684328, 2022). "Cytoplasmic retention of cyclin B1 has been shown to maintain G2/M arrest and play a role in the regulation of cell cycle checkpoint and prevention of cancer progression." (PMID 33931611, 2021). "Although the binding of p21 to CDK1 and its stability are involved in the nuclear accumulation of inactive CDK1–cyclin B1 complexes and the induction of apoptosis, caspase-3-mediated p21 cleavage confers DNA damage-induced apoptosis of cancer cells." (PMID 34064109, 2021). "Abnormal mitosis induced by CCNB1/CDK1 complex is an enormous element of cancer development or progression." (PMID 34858850, 2021). "Consistent with the present results, the overexpression of cyclin B1 has been reported to sensitize cancer cells to PTX." (PMID 33710778, 2021).